PLEK2 (pleckstrin 2)
Diseases named in the same sentence as PLEK2 in open-access papers (continued):
Sharing a sentence is not in itself a finding about the gene and the disease.
lung adenocarcinoma (4 papers, 2021 to 2025). A carcinoma that arises from the lung and is characterized by the presence of malignant glandular epithelial cells. "Among the genes included in the prognostic model, PLEK2 has been reported in five studies as a prognostic marker for lung adenocarcinoma." (PMID 37781711, 2023).
anemia (3 papers, 2021 to 2023). A reduction in the number of red blood cells, the amount of hemoglobin, and/or the volume of packed red blood cells. "However, PLEK2-knockout mice were largely normal at the young age but showed mild anemia with age due to ineffective erythropoiesis, suggesting that PLEK2 plays a critical role in stressed erythropoiesis." (PMID 34869363, 2021). "Notably, Plek2-KO mice exhibited only minor age-related anemia without other severe phenotypes, which indicates that Plek2’s proproliferative function is tumor specific." (PMID 36719747, 2023).
esophageal squamous cell carcinoma (3 papers, 2021 to 2024). Esophageal squamous cell carcinoma (ESCC) is a type of esophageal carcinoma (EC) that can affect any part of the esophagus, but is usually located in the upper or middle third. "Our previous studies highlighted that PLEK2 contributes to metastasis and chemoresistance in esophageal squamous cell carcinoma (ESCC)." (PMID 39546161, 2024).
glioma (3 papers, 2021 to 2024). A benign or malignant brain and spinal cord tumor that arises from glial cells (astrocytes, oligodendrocytes, ependymal cells). "Further investigation is needed pertaining to PLEK2 and GCSH to analyze their prognostic accuracy and ability to differentiate between GBM versus alternative gliomas." (PMID 36837779, 2023). "In addition, GCSH expression is clearly lowered with increasing glioma grade, while that of PLEK2 and RRM2 is clearly elevated; therefore, GCSH does not fit the premise of targeted therapy, i.e., biological pathway inhibition." (PMID 34204789, 2021).
head and neck squamous cell carcinoma (3 papers, 2021 to 2024). A squamous cell carcinoma that arises from any of the following anatomic sites: lip and oral cavity, nasal cavity, paranasal sinuses, pharynx, larynx, and salivary glands. "However, the role of PLEK2 in head and neck squamous cell carcinoma (HNSCC) remains to be elucidated." (PMID 34331382, 2021).
myeloproliferative neoplasm (3 papers, 2021 to 2024). A clonal hematopoietic stem cell disorder, characterized by proliferation in the bone marrow of one or more of the myeloid (i.e., granulocytic, erythroid, megakaryocytic, and mast cell) lineages. "In another report, PLEK2 was found to be an effector of the JAK2/STAT5 pathway and an important regulator in the pathogenesis of JAK2V617F-induced myeloproliferative neoplasms, suggesting that PLEK2 is a feasible therapeutic target of myeloproliferative neoplasms." (PMID 34394345, 2021).
prostate carcinoma (2 papers, 2020 to 2021). A carcinoma that arises from epithelial cells of the prostate gland. "PLEK2 is identified as an prognosis factor for prostate cancer, lung adenocarcinoma and head and neck squamous cell carcinoma in independent bioinformatics analysis with gene signature-based risk assessment models." (PMID 34869363, 2021). "Although two recent studies showed that PLEK2 mRNA expression is down-regulated in multiple myeloma bone marrow progenitor cells and prostate cancer, its expression is thought to be positively correlated with the poor prognosis." (PMID 34869363, 2021). "FAM72D, ARHGAP33, TACR2, PLEK2, and FA2H were identified as independent prognosis factors in prostate cancer patients." (PMID 32566639, 2020).
cholecystolithiasis (1 paper, 2019). Single or multiple, ovoid or irregular, solid particles that are formed from bile, cholesterol, and calcium in the gallbladder cavity. "PLEK2 expression was higher in GBC tissues than that in cholecystolithiasis tissues (P < 0.05)." (PMID 31182136, 2019). "Additionally, PLEK2 had higher expression in GBC tumor tissues compared to cholecystolithiasis tissues and high PLEK2 expression was positively correlated with liver metastasis and prognosis in GBC patients." (PMID 31182136, 2019). "In this study, we found that PLEK2 had higher expression in GBC tumor tissues compared to non-cancerous adjacent tissues and cholecystolithiasis tissues." (PMID 31182136, 2019).
depression (1 paper, 2020). "In the bivariate meta-GWAS of broad depression phenotype and recurrent MDD, the PLEK2 locus reached genome-wide significance (p = 3.05 × 10–10) but was not replicated." (PMID 30626913, 2020).
large cell lung carcinoma (1 paper, 2024). "Specifically, we targeted PLEK2 in MDA-MB-231 (BRCA), H2052 (MESO), KYSE-450 (ESCA), A549 (LUAD), H226 (LUSC), H460 (large cell lung carcinoma), PANC-1 (PAAD), UM-UC-3 (BLCA), and HCT-116 (COAD) cell lines." (PMID 39546161, 2024).
Lewis lung carcinoma (1 paper, 2024). "In vivo studies using a Lewis lung carcinoma (LLC) model confirmed that PLEK2 knockdown suppressed tumor growth and enhanced the efficacy of PD-1 immunotherapy." (PMID 39546161, 2024).
lymph node metastasis (1 paper, 2021). "We also found a significant association between patients with lymph node metastasis and overexpression of BMP7 (47.4%, P=0.005), CALD1 (42.1%, P=0.020), CDH1 (52.6%, P=0.001), COL3A1 (42.1%, P=0.020), EGFR (47.4%, P=0.005), ERBB3 (57.9%, P=0.000), PLEK2 (47.4%, P=0.024), and TCF4 (52.6%, P=0.001)." (PMID 34527572, 2021).
multiple myeloma (1 paper, 2021). "In addition, a recent bioinformatics study has also suggested that PLEK2 is significantly associated with survival of patients, as well as a novel therapeutic target for multiple myeloma." (PMID 34869363, 2021).
tongue cancer (1 paper, 2021). A malignant neoplasm affecting the tongue. "In Ye Head‐Neck statistics, PLEK2 was higher in tongue carcinoma (FC = 2.528)." (PMID 34331382, 2021).
tumor (24 papers, 2011 to 2025). "There was a statistically significant difference between the two groups in person neoplasm cancer status (p = 0.013) as well as tumor basal diameter (p = 0.039), indicating higher PLEK2 expression was associated with worse clinical characteristics." (PMID 39687904, 2024). "Significant differences were noted in cancer status and tumor basal diameter, indicating that high PLEK2 expression is linked to poorer clinical outcomes in UVM patients." (PMID 39687904, 2024). "To identify potential strategies to mitigate the tumor-enhancing effects of Plek2, we assessed drug sensitivity associated with its expression." (PMID 39546161, 2024). "This contradiction was possibly due to the complex role of PLEK2 in immunotherapy response, involving an interplay between enhancing mutation burden and promoting immune evasion strategies of the tumor." (PMID 39546161, 2024). "Bioinformatics analysis indicated a positive correlation between PLEK2 expression and macrophage infiltration, suggesting that PLEK2 might have promoted the recruitment or activation of tumor-associated macrophages (TAMs)." (PMID 39546161, 2024). "However, our research indicated a positive correlation between PLEK2 expression and tumor mutation burden (TMB) in most cancers, which typically suggested that higher PLEK2 expression could be associated with a more responsive tumor to immunotherapy." (PMID 39546161, 2024). "In our study, PLEK2 was significantly overexpressed in tumor tissues and promoted proliferation, migration, and colony formation in LUAD cell lines." (PMID 40552290, 2025). "Considering that cancer stem cells are responsible for the tumor metastasis, we further evaluated the effect of PLEK2 on the CRC metastasis driven by CCSCs in vivo." (PMID 40682666, 2025). "Individual CRC datasets from Gene Expression Omnibus (GEO) databases also showed that PLEK2 was significantly upregulated in primary tumor tissues of CRC compared with adjacent normal tissues." (PMID 40682666, 2025). "Although pleckstrin family members such as PLEK2 and CNK1 have been implicated in tumor progression through PI3K-Akt signaling and KRAS-mediated immune modulation, the role of classical PLEK (Plek1) in solid tumors remains largely unexplored." (PMID 40895569, 2025). "To confirm this observation in clinical specimens, we assessed PLEK2 expression in paired tumor and adjacent normal tissues from LUAD patients who underwent surgical resection at Tianjin Chest Hospital." (PMID 40552290, 2025). "To explore the correlation between Plek2 knockdown and immunomodulatory molecules, we collected tumor tissues from C57BL/6 mice bearing tumors and extracted RNA for RT-PCR analysis of Cd276, Cd274, and Lgals9 expression." (PMID 39546161, 2024). "To determine the specific cell types expressing PLEK2 in tumor tissues, we analyzed its single-cell expression across 88 datasets using the Tumor Immune Single-cell Hub (TISCH) online tool." (PMID 39546161, 2024). "To further elucidate the functional role of PLEK2 in tumor cells, we performed transient siRNA-mediated knockdown of PLEK2 in various human cancer cell lines." (PMID 39546161, 2024). "Pleckstrin-2 (PLEK2), a member of the pleckstrin family, has been implicated in processes critical to tumor progression, but its role across cancers remains underexplored." (PMID 39546161, 2024). "Mechanistically, PLEK2 knockdown was associated with reduced AKT pathway activation, diminished tumor-associated macrophage infiltration, and increased CD8 T cell presence." (PMID 39546161, 2024). "Our findings indicated that PLEK2 played a significant role in tumor progression by promoting cell proliferation and migration." (PMID 39546161, 2024). "Single-cell RNA sequencing data indicated that PLEK2 expression is predominantly found in tumor cells and macrophages within the tumor microenvironment." (PMID 39546161, 2024).
tumor (continued). "To further elucidate the influence of PLEK2 on tumor immunity, we conducted a pan-cancer Gene Set Enrichment Analysis (GSEA)." (PMID 39546161, 2024). "Specifically, in the LLC model, Plek2 knockdown significantly reduced tumor growth rates and tumor weights in vivo." (PMID 39546161, 2024). "Clinical comparisons indicated significant differences in cancer status (p = 0.013) and tumor diameter (p = 0.039) between high and low PLEK2 expression groups." (PMID 39687904, 2024). "Single-cell analysis showed that PLEK2 was highly expressed in both macrophages and epithelial cells, with PLEK2 expression in epithelial cells potentially enhancing tumor cell proliferation and TME interactions." (PMID 39546161, 2024). "Considering that the tumor-promoting effects of the Wnt/Ca2+ signaling pathway have received increasingly widespread attention, we further analyzed the correlation between PLEK2 and molecules in Wnt/Ca2+ signaling pathway using GEPIA2." (PMID 39687904, 2024). "Plek2 knockdown significantly reduced tumor growth rates and tumor weights by day 14 after transplantation, while Plek2 overexpression markedly increased both." (PMID 39546161, 2024). "In our LLC mouse model, Plek2 knockdown enhanced the efficacy of PD-1 antibodies, resulting in a more pronounced reduction in tumor growth." (PMID 39546161, 2024). "Conversely, Plek2 overexpression fostered an immunosuppressive tumor microenvironment, likely contributing to resistance to PD-1 therapy." (PMID 39546161, 2024). "Functional experiments demonstrated that PLEK2 knockdown suppressed tumor cell proliferation and migration both in vitro and in vivo." (PMID 39546161, 2024). "Recognizing the pivotal role of animal studies in understanding the mechanisms behind tumor immunotherapy, we explored the prognostic capabilities of Plek2 in mouse models using the TISMO database." (PMID 39546161, 2024). "Targeting PLEK2 not only suppressed tumor proliferation and migration but also enhanced the efficacy of immunotherapy, particularly PD-1 blockade." (PMID 39546161, 2024). "Single-cell RNA sequencing further indicated predominant expression of PLEK2 in tumor cells and macrophages within the tumor microenvironment." (PMID 39546161, 2024). "Overexpression of PLEK2 promoted tumor growth and created an immunosuppressive microenvironment by modulating immune cell infiltration and immunosuppressive molecules." (PMID 39546161, 2024). "Under immunocompetent conditions, consistent with prior in vivo experiments, Plek2 knockdown continued to inhibit tumor growth." (PMID 39546161, 2024). "The outcomes of our study are expected to elucidate the potential role of PLEK2 in tumor immunology and offer fresh insights for the advancement of immunotherapy research." (PMID 39546161, 2024). "To further validate the role of Plek2 in tumor growth, we conducted in vivo experiments by implanting LLC cells into BALB/c nude mice." (PMID 39546161, 2024). "Overexpression of PLEK2 significantly promoted epidermal-mesenchymal transformation and tumor migration." (PMID 36969247, 2023). "RT-PCR, western blot, wound healing assays, and siRNA methods were further used to investigate the role of PLEK2 in tumor behaviors." (PMID 37910672, 2023). "The expression of two proteins (FERMT1, and PLEK2) in LUAD cancer were higher in tumor tissues (66.6%) than in normal tissues." (PMID 36428765, 2022). "By detecting the level of PLEK2 in tumour tissues from ESCC patients who received chemotherapy, we found that high PLEK2 expression linked to the OS of the chosen patients." (PMID 34601488, 2021). "The role of PLEK2 in tumor development is gradually being recognized, and it serves as a potential diagnostic and prognostic biomarker as well as an attractive target for the treatment of cancers." (PMID 34869363, 2021). "Despite conclusive evidence supporting PLEK2 is involved in cell migration and invasion, its regulatory roles in tumor cell invasion and metastasis remains largely limited." (PMID 34869363, 2021).
tumor (continued). "A chi-square test demonstrated that PLEK2 protein was prominently connected with the tumour grade (P = 0.025), tumour size (P = 0.033), lymph node invasion (P = 0.045), distant metastasis (P = 0.011), and advanced TNM stage (P = 0.039)." (PMID 34394345, 2021). "Conversely, the knockdown of PLEK2 significantly suppressed tumour growth and weight compared with the level of suppression in the nontarget shRNA control groups." (PMID 34394345, 2021). "Since PLEK2 induces cell spreading and guides tumor progression and metastasis, the development of new targeted therapy aimed at this oncogenic molecule is of utmost importance." (PMID 34204789, 2021). "Results of IHC conducted on tumour tissues indicated that the expression of PLEK2 was gradually increased as the dosage increased." (PMID 34601488, 2021). "To identify the driver genes in GBC metastasis, we performed a mRNA microarray analysis of metastatic GBC and paired non-tumor samples and found several genes upregulated, including pleckstrin-2 (PLEK2)." (PMID 31182136, 2019). "To identify the driver genes in GBC metastasis, we performed a mRNA microarray of metastatic GBC and paired non-tumor samples, and found PLEK2 was markedly upregulated in GBC tissues." (PMID 31182136, 2019). "Altogether, the role of PLEK2 in tumor metastasis is being recognized gradually, but the clear mechanism of how it works is poorly understood." (PMID 31182136, 2019). "The clinicopathologic analyses showed PLEK2 expression was positively correlated with tumor TNM stage, distant metastasis and PLEK2 was an independent predictor of overall survival (OS) in GBC patients." (PMID 31182136, 2019). "As expected, PLEK2 knockdown led to the marked reduction in tumor growth of HCT116 cells." (PMID 40682666, 2025). "High PLEK2 expression was associated with worse overall survival (OS), disease-free survival (DFS), disease-specific survival (DSS), and progression-free survival (PFS) in several tumor types, including LUAD." (PMID 40552290, 2025). "qRT-PCR analysis confirmed that PLEK2 was significantly overexpressed in tumor tissues." (PMID 40552290, 2025). "PLEK2 was significantly upregulated in multiple tumor types, including LUAD." (PMID 40552290, 2025). "Given the heterogeneous nature of cancer and the variability in responses to immunotherapy, elucidating the role of PLEK2 across multiple tumor types could aid in the identification of novel therapeutic targets and improve the precision of immunotherapy." (PMID 39546161, 2024). "This function may be closely related to the invasion and metastasis of tumors, and an increasing number of studies are now beginning to focus on the aspect of PLEK2 promoting tumor metastasis." (PMID 39687904, 2024). "Notably, the combination of Plek2 knockdown and PD-1 antibody treatment significantly suppressed tumor growth rates and weights compared to controls." (PMID 39546161, 2024). "This suggested that PLEK2 inhibition may have alleviated immunosuppression, thereby enhancing anti-tumor immune responses." (PMID 39546161, 2024). "In our in vivo experiments, Plek2 knockdown was associated with decreased expression of Cd276 (B7-H3), suggesting that PLEK2 might foster an immunosuppressive tumor microenvironment (TME)." (PMID 39546161, 2024). "Targeting PLEK2 might suppress tumor growth and overcome immunotherapy resistance, offering a promising biomarker and therapeutic target to improve cancer treatment outcomes." (PMID 39546161, 2024). "Consistently across all datasets, the elevated expression of PLEK2 in monocytes/macrophages and tumor cells suggested that PLEK2 might play a significant role in tumor immunity." (PMID 39546161, 2024). "Understanding how PLEK2 influences tumor progression and immune responses could provide valuable insights for enhancing therapeutic strategies." (PMID 39546161, 2024). "Notably, PLEK2 exhibited higher expression levels in tumor cells and immune cells such as macrophages and monocytes." (PMID 39546161, 2024).